GOLGA6L3P (golgin A6 family like 3, pseudogene)
Synonyms: GOLGA6L3
Gene: Transcribed unprocessed pseudogene on chromosome 15 (85,240,472 to 85,247,170, forward strand). Ensembl gene ENSG00000188388.
Diseases named in the same sentence as GOLGA6L3P in open-access papers:
GOLGA6L3P is named in the same sentence as 1 disease in open-access papers, as found by Europe PMC text mining. Sharing a sentence is not in itself a finding about the gene and the disease.
GOLGA6L3P shares sentences with these, for which no sentence is quoted: tumor (1 paper).